FSHB (follicle stimulating hormone subunit beta)
Diseases named in the same sentence as FSHB in open-access papers (continued):
Sharing a sentence is not in itself a finding about the gene and the disease.
Infertility (25 papers, 2010 to 2026). "This is due to the well‐established fact that an increased prevalence of the FSHB‐211 T allele is associated with lower follicle‐stimulating hormone (FSH) values in infertile men." (PMID 40105106, 2026). "We found evidence for shared variants between hormones and infertility at the FSHB locus associated with FSH, LH and testosterone (PP >84.8% for colocalization with F-ANOV), and the ARL14EP locus associated with LH (PP 89.3% for colocalization with F-ANOV)." (PMID 40229599, 2025). "In humans, FSHβ mutations lead to azoospermia and infertility, although men with mutation in FSHR are phenotypically normal with some subfertility, similar to deficient mice with the same mutation." (PMID 34576272, 2021). "Although these data point at a number of potential molecular targets only three causative mutations, resulting in male sub- or infertility in cattle have been determined in the FSHB, TMEM95, and ARMC3 gene hitherto." (PMID 31963602, 2020). "In the present study, we included 340 fertile males and 255 infertile males, consisting of 166 with azoospermia or severe oligozoospermia, and 89 with oligospermia, and we investigated the association between FSHB, FSHR gene polymorphisms and male infertility." (PMID 28764642, 2017). "In total five mutations in FSHB have been reported in three male and six female patients, all having a severely impaired sexual development and infertility." (PMID 20488225, 2010). "In light of this evidence, in our routine clinical practice, FSHB c.-211G > T polymorphism analysis is used to identify a subgroup of infertile men who will respond well to FSH therapy and who have spermatogenic impairment and low or inappropriately normal FSH plasma levels." (PMID 39202711, 2024). "Since the FSHB SNP was identified as a segregation marker, we suggest introducing diagnostic genotyping into the clinical routine for infertility workups of idiopathic infertile men, which will help identify men with secondary functional hypogonadism and isolated FSH deficiency." (PMID 34992580, 2021). "The FSH‐value in infertile men the FSH‐value was 3.8 ± 2.2 when they had the genotype FSHB c.211GG, and it was significant lower, then they had the genotype FSHB c.211GT/TT (3.1 ± 1.6, p < 0.001)." (PMID 40105106, 2026). "Subgroup analysis of the infertile men revealed that the FSH value was significantly lower in those with the genotype FSHB c.‐211 GT/TT compared to those with the genotype FSHB c.‐211 GG (p < 0.001)." (PMID 40105106, 2026). "Loss-of-function variants in FSHB and LHB have been associated with infertility, primary amenorrhoea, azoospermia and variable impairment of pubertal development." (PMID 36517585, 2023). "Surprisingly, across all diverse phenotypes of infertility, the strongest segregation markers were FSHB c.-211G>T, FSH, and bi-testicular volume." (PMID 34992580, 2021). "Roy15 showed a marked (>10‐fold) elevation of ovarian AMH mRNA in FSHβ−/− infertile mice compared to wild‐type or FSHβ−/−/hFSHβWT controls, supporting the inhibitory role of FSH on AMH expression in this system." (PMID 33855196, 2021). "Previous studies, in particular one study from our group, suggested that infertile patients with FSHB c.-211G > T T homozygous better respond to FSH treatment, demonstrating, in comparison to carriers of the other genotype, a noteworthy increase in spermatogenesis following therapy." (PMID 39202711, 2024). "In men, low fertility with a quantitative reduction in spermatogenesis occurs without FSHR function, while mutations in the FSHβ subunit can lead to azoospermia and infertility." (PMID 39140811, 2024). "In addition, FSHB c.-211G > T G homozygous was more frequently detected in patients with altered semen analysis in 190 infertile men, compared to 50 fertile controls." (PMID 39202711, 2024).
Infertility (continued). "In the future, pharmacogenomics of FSHR and FSHB as well as innovative compounds may be considered to develop new therapeutic strategies in the management of infertility." (PMID 35349114, 2022). "Genetic variant −211 G>T FSHB (rs10835638) was determinant of serum FSH and LH levels in eumenorrheic healthy and infertile women, and associated with the response to controlled ovarian hyperstimulation, LH concentration, antral follicle counting, oocytes retrieval and embryos, and PCOS." (PMID 36430184, 2022). "While measuring FSH and assessing testicular volume are routine procedures in infertility workup, the FSHB c.-211G>T single nucleotide polymorphism is not yet included in routine clinical diagnostics for infertile men." (PMID 34992580, 2021). "Specifically, FSHβ knockout female mice were infertile due to a block in folliculogenesis before antral follicle formation whereas TG female mice overexpressing human FSHβ under the control of a mouse MT promoter were also infertile due to disrupting ovarian folliculogenesis." (PMID 22860114, 2012). "Overexpression of FSHB could cause polycystic ovary syndrome as in female FSH overexpressing mice, whereas severe reduction in FSHB transcription and FSH production could cause infertility in females or poor sperm quality in males." (PMID 20488225, 2010). "Two studies assessing the effects of FSHB rs10835638 on basal FSH levels, in women with known infertility compared with a control group of healthy women, reported that women expressing the T allele showed significantly higher FSH basal levels." (PMID 35178027, 2021). "However, in men with the genotype FSHB c.‐211 GT/TT, a significantly higher FSH value was observed in fertile men (4.2 ± 2.5) compared to infertile men (3.1 ± 1.6) (p < 0.001)." (PMID 40105106, 2026). "While hormone-associated variants near FSHB and ARL14EP colocalised with signals for anovulatory infertility, we found no rg between female infertility and reproductive hormones (P>0.05)." (PMID 38562841, 2024). "The genetic parameter of FSHB c.-211G>T in combination with the established parameters FSH and testicular volume should attract more attention in future clinical workups of idiopathic infertile men." (PMID 34992580, 2021).
Azoospermia (8 papers, 2016 to 2024). Absence of any measurable level of sperm,whereby spermatozoa cannot be observed even after centrifugation of the semen pellet. "By contrast, all five men discovered as isolated cases of inactivating FSHβ mutations were diagnosed with azoospermia and infertility." (PMID 34884539, 2021). "In humans, distinct fertility phenotypes, ranging from azoospermia to oligozoospermia, have been described in carriers of the FSHB or FSHR mutations, respectively." (PMID 34884539, 2021). "In humans, fertility phenotypes in carriers of inactivating FSHB or FSHR mutations varies from azoospermia to mild reduction of spermatogenesis." (PMID 30619093, 2018). "Additional genetic and/or environmental factors besides the FSHB mutations may also explain the azoospermia found in the mutation carriers." (PMID 30619093, 2018). "Rare mutations in the FSHB gene cause truncation of the FSH-β protein and result in hypogonadism and primary amenorrhoea in females and, in a male, delayed puberty with azoospermia." (PMID 26732621, 2016). "Men carrying loss-of-function mutation in the gene encoding the ligand (FSHB) or its receptor (FSHR) present, respectively, with azoospermia or suppressed spermatogenesis." (PMID 30619093, 2018).
hypogonadism (8 papers, 2011 to 2023). A disorder characterized by decreased function of the gonads. "Genetic deletion of the FSHβ subunit (FSHβ-/- mice) or FSH receptor (FSHR-/- mice) protects against bone loss despite severe hypogonadism, demonstrating a contribution of FSH in hypogonadal bone loss." (PMID 33767633, 2021). "Interestingly, Wdr11-null mice have decreased LHβ-subunit but normal FSHβ-subunit expression, suggesting the existence of a dissociated hypogonadism, which could explain the observation in our patient." (PMID 35722485, 2022).
polycystic ovary syndrome (6 papers, 2010 to 2022). A disorder that manifests as multiple cysts on the ovaries. "Genetic association studies have identified signals at the FSHB locus associated with age at menopause, polycystic ovary syndrome (PCOS) and levels of LH." (PMID 26732621, 2016). "For rs11031002, these include LH level (beta = 0.221 for allele A); serum levels of protein CGA; FSHB (beta = −0.162 for allele A); polycystic ovary syndrome (PCOS) (OR = 1.24 for allele A); and bone mineral density (beta = 0.02 for allele T)." (PMID 36430184, 2022). "FSH is required for normal fertility and genetic variants at the FSHB locus are associated with age at menopause and polycystic ovary syndrome (PCOS)." (PMID 26732621, 2016). "A recent genome-wide association study (GWAS) of polycystic ovary syndrome (PCOS) in European cohorts has identified six susceptibility loci mapping to 11q22.1 (YAP1), 2p21 (THADA), 11p14.1 (FSHB), 2q34 (ERBB4), 12q21.2 (KRR1), and 5q31.1 (RAD50)." (PMID 28195137, 2017). "Among the three common synonymous changes described in the coding region of FSHB, the 2623T>C (Tyr58Tyr) in exon 3 has been demonstrated to be more frequent among obese patients with polycystic ovary syndrome (PCOS) than in healthy females." (PMID 20488225, 2010).
osteoporosis (5 papers, 2018 to 2026). A condition of reduced bone mass, with decreased cortical thickness and a decrease in the number and size of the trabeculae of cancellous bone (but normal chemical composition), resulting in increased fracture incidence. "Additionally, FSHB was shown to be causally associated and directionally consistent with all osteoporosis-related traits measured by DXA." (PMID 39526243, 2024). "A 13-aminoacid-long peptide polyclonal antibody that is capable of selectively binding and inhibiting the FSHβ subunit has been used in animal studies to investigate the possible role of FSH in osteoporosis prevention." (PMID 31581477, 2019). "Hence, these findings support that C/EBPβ dictates FSHβ transcription and blocking AEP by its inhibitor represses C/EBPβ-mediated FSHβ levels, exerting prominent therapeutic efficacy toward osteoporosis." (PMID 41844581, 2026). "In fact, the rs6166 FSHR genotype might help in stratifying the risk of developing osteoporosis and a monoclonal antibody against the FSHβ chain has shown promising results for the treatment of osteoporosis in the animal model." (PMID 31581477, 2019). "Hence, the development and the use of a monoclonal antibody against the FSHβ chain might be hypothesized for the treatment of osteoporosis." (PMID 31581477, 2019). "Inactivation of AEP, either by knockout of AEP or its small molecular inhibitor, antagonizes C/EBPβ and suppresses FSHβ levels, attenuating ovariectomy (OVX)-elicited osteoporosis." (PMID 41844581, 2026). "FSH receptor (FSHR) and FSHβ knockout ovariectomized mice do not develop bone loss, suggesting that the FSH/FSHR pathway is involved in the pathogenesis of osteoporosis." (PMID 31581477, 2019).
ovarian carcinoma (5 papers, 2013 to 2023). A malignant neoplasm originating from the surface ovarian epithelium. "Before the in vivo ovarian tumor bioimaging study, the potential cytotoxicity of DNA and FSHβ modified DCNPs were evaluated in human ovarian carcinoma cell line CaOV3." (PMID 30042434, 2018).
breast carcinoma (4 papers, 2017 to 2024). "Finally, the overlap between the expression pattern at the FSHβ locus and ERBB2 signaling is supported by the relationship between gonadotropins, estradiol and HER-2 upregulation in breast cancer patients." (PMID 28068351, 2017).
pituitary adenoma (3 papers, 2017 to 2021). "In another study, pathological examination of the surgical specimen for pituitary adenoma in girls with CPP showed strong immunostaining for FSHβ." (PMID 34069752, 2021). "Our results show that miR-21 can regulate the expression levels of FSHb in rat pituitary cells and reveal that miR-21 might participate in the regulation of animal reproduction in addition to the regulation of pituitary adenomas." (PMID 28402262, 2017).
hyperandrogenism (2 papers, 2015 to 2019). Excessive secretion of androgens from the adrenal glands or gonads. "Pathophysiological functions of genes are primarily responsible for the synthesis of proteins that have role in PCOS before hyperandrogenism including GnRHR, FSHβ, FSHR, LHCGR, CYP19A1, HSD17B, AR and SHBG, and their effects in PCOS of human have been confirmed." (PMID 30944702, 2019).
male infertility (2 papers, 2017 to 2024). The inability of the male to effect fertilization of an ovum after a specified period of unprotected intercourse. "Then the most common FSHR allelic variants in the core promoter and exon 10, and the FSHB variants in the core promoter were genotyped with respect to male infertility status using the Mass ARRAY platform." (PMID 28764642, 2017). "However, the associations between these SNPs in the FSHR gene and FSHB and male infertility remain uncertain." (PMID 28764642, 2017). "In terms of male infertility with multifactorial etiology, further studies with larger sample sizes and different ethnic backgrounds or other risk factors are warranted to clarify the potential role of FSHB and FSHR polymorphisms in the pathogenesis of male infertility." (PMID 28764642, 2017). "Several studies have been produced and analyzed in the present review in order to understand which markers are prognostic of a good response to FSH treatment in male infertility, such as spermatid count, testicular cytology, and the assessment of the polymorphisms in both FSHR and FSHB genes." (PMID 39202711, 2024).
Obesity (2 papers, 2015 to 2018). Accumulation of substantial excess body fat. "FTO (Fat mass and obesity associated gene; rs9939609), FSHB (Follicle stimulating hormone beta subunit; rs6169), FSHR (Follicle stimulating hormone receptor; rs6165/rs6166), and INSR (Insulin receptor; rs1799817) genes were genotyped using HRM assay." (PMID 30596735, 2018).
Autoimmunity (1 paper, 2012). The occurrence of an immune reaction against the organism's own cells or tissues. "Similarly to insulin gene polymorphisms affecting central tolerance through the level of gene expression in thymus, we were looking for an association between the two FSHB core haplotypes and autoimmunity against FSH." (PMID 22007255, 2012).
chronic endometritis (1 paper, 2020). A non-granulomatous or granulomatous chronic inflammation of the endometrium. "Among the obtained models of gene–environment interactions, the most optimal for prediction was rs12324955 FTO × rs11031010 FSHB × chronic endometritis × aborts (OR = 3.90, Test." (PMID 33552117, 2020).
corticotroph adenoma (1 paper, 2020). "Intriguingly, we revealed distinct groups as follows: 1) somatotroph adenoma: high POU1F1 and high DLK1; 2) lactotroph adenoma: high POU1F1 and low DLK1; 3) gonadotroph adenoma: high FSHB and low DLK1, followed by high GATA2 and low DLK1; and 4) corticotroph adenoma: high TBX19 and low DLK1." (PMID 33472171, 2020). "Based on the transcriptomic analysis of 172 PitNETs, we suggest a solution as follows: 1) somatotroph adenoma: high PIT1 and high DLK1; 2) lactotroph adenoma: high PIT1 and low DLK1; 3) gonadotroph adenoma: high FSHB and low PIT1/DLK1; and 4) corticotroph adenoma: high TBX19 and low PIT1/DLK1." (PMID 33472171, 2020).
Cushing syndrome (1 paper, 2025). Cushing's syndrome (CS) encompasses a group of hormonal disorders caused by prolonged and high exposure levels to glucocorticoids that can be of either endogenous (adrenal cortex production) or exogenous (iatrogenic) origin. "LC-TPIT primarily includes genes implicated in Cushing syndrome (e.g., POMC, EGFR), and LC-SF1 is enriched for components of the GnRH signaling pathway (e.g., LHB, FSHB)." (PMID 41253784, 2025).
hyperthyroidism (1 paper, 2025). Overactivity of the thyroid gland resulting in overproduction of thyroid hormone and increased metabolic rate. "A study examining the effect of experimentally-induced hyperthyroidism on reproductive dysfunction and gonadotropin secretion in female rats reported decreased serum TSH, FSH, and PRL concentrations, as well as pituitary FSHβ and TSH gene expression levels, in hyperthyroid animals." (PMID 40610792, 2025).
obstetric disorder (1 paper, 2024). Disorder associated with pregnancy, childbirth, and puerperium. "FSHB was predominantly associated with gynecologic and obstetric disorders, underscoring its relevance in reproductive health." (PMID 39526243, 2024). "The significant function of FSHB in the female reproductive system has been well-documented, which might explain the genetic association of FSHB with gynecological and obstetric disorders observed in Phewas analysis." (PMID 39526243, 2024). "Phewas analysis showed that FSHB was predominantly associated with gynecologic and obstetric disorders, which may partially explain the gender differences in the genetic association between FSHB and HBMD." (PMID 39526243, 2024).
seminoma (1 paper, 2023). A radiosensitive malignant germ cell tumor found in the testis (especially undescended), and extragonadal sites (anterior mediastinum and pineal gland). "Expression of FSHB was basically restricted to a small fraction of seminomas and LHB was strongly upregulated in seminoma as compared with NSGCT, in line with the differences in serum levels of our cohort." (PMID 37669975, 2023).
small cell carcinoma (1 paper, 2010). A neuroendocrine carcinoma composed of small malignant cells which are often said to resemble "oat cells" under the microscope. "The same is true of transduction through Gs, AC, PKA, and CREB toward LHβ and FSHβ, suggesting that both routes play a role in small cell carcinoma." (PMID 20187943, 2010).